SOX2 (SRY-box transcription factor 2)
Diseases named in the same sentence as SOX2 in open-access papers (continued):
Sharing a sentence is not in itself a finding about the gene and the disease.
metastatic carcinoma (5 papers, 2015 to 2022). A carcinoma which has spread from the original site of growth to another anatomic site. "In our meta-analysis, we have attempted to estimate the prognostic effect of CSCs, CD133, and SOX2 using multivariable analysis in patients with advanced or metastatic cancer." (PMID 30693028, 2019). "To clarify the correlation between the expression of stem cell markers (CD133 and SOX2) and the prognosis in advanced or metastatic cancer patients, we investigated the relationship between the expression of these two markers and survival of the samples." (PMID 30693028, 2019). "Taken together, we use patient-derived paired primary and metastatic cancer organoids to model CRC metastasis and illustrate that SOX2 is associated with CRC progression and may serve as a potential prognostic biomarker and therapeutic target of CRC." (PMID 32883331, 2020). "Therefore, it remains important to better understand the characteristics of CSCs, CD133, and SOX2 for valuable therapeutic and prognostic targets in clinical practice to predict disease outcomes in advanced or metastatic cancer patients." (PMID 30693028, 2019). "More importantly, the expression of Oct4, Sox2, Gli1, CD44, CD133, p-AKT, and p-ERK was significantly higher in metastatic cancer tissues than in primary cancer tissues." (PMID 26769843, 2016). "Furthermore, a positive correlation of the gene expression from two different metastatic cancer data suggesting the involvement of KDM6B in regulating HIF1α, SOX2, and CD44 further indicates the stemness regulatory function of KDM6B in various cancer types." (PMID 35186918, 2022).
neuroendocrine carcinoma (5 papers, 2020 to 2024). A malignant neuroendocrine neoplasm composed of cells containing secretory granules that stain positive for NSE and chromogranin. "Additionally, high expression of Sox2 is present in a large proportion of patients with an advanced neuroendocrine cancer." (PMID 32596945, 2020). "CpGs of lower methylation in VP-MCC cell lines were associated with neuroendocrine marker genes such as SOX2 and INSM1, or linked to binding sites of EZH2 and SUZ12 of the polycomb repressive complex 2, i.e., genes with an impact on carcinogenesis and differentiation of neuroendocrine cancers." (PMID 34667274, 2022). "Protein array analysis showed expression of multiple intracellular transcription factors involved in neuroendocrine cancer pathobiology—Snail, GATA4, FoxA2, Sox-2, PDX-1 and surface molecule (E-cadherin)." (PMID 39103560, 2024). "Antibody array protein chip analysis of transcription factors in 3DiNET ORION cells revealed expression of several intracellular transcription factors involved in neuroendocrine cancer pathobiology—Snail, GATA4, FoxA2, Sox-2, PDX-1 and E-cadherin." (PMID 39103560, 2024). "The associations of SOX2 and/or high-risk (HR)-HPV RNA in situ hybridization (RISH) levels with clinicopathological characteristics and prognostic outcomes for 88 neuroendocrine carcinoma (NEC) cases were analyzed." (PMID 33789601, 2021). "SOX2 expression is highly sensitive for MCC (92%), and is highly specific for MCC compared to other cutaneous carcinomas, as well as 70% specific for MCC compared to other neuroendocrine carcinomas." (PMID 39136002, 2024).
odontogenic tumors (5 papers, 2020 to 2025). "Continued investigation with larger cohorts and follow-up data is warranted to validate the clinical utility of Sox2 as a tumor stem cell–associated prognostic marker in odontogenic tumors and cysts." (PMID 41176605, 2025). "Future studies with larger cohorts, incorporating other molecular techniques, functional analyses and long-term follow-up are warranted to validate Sox2 as a prognostic biomarker in odontogenic tumors and cysts." (PMID 41176605, 2025). "Several recent studies, consistent with our findings, also reported both cytoplasmic and nuclear immunoreactions for SOX2, with intense staining in malignant and aggressive odontogenic tumors." (PMID 41176605, 2025). "This indicates that while nuclear SOX2 drives stemness and pluripotency, its presence in the cytoplasm may have distinct, and as yet not fully understood, functions in odontogenic tumor progression." (PMID 41176605, 2025). "This may reflect the biological behavior of odontogenic tumors, in which Sox2-positive cells exhibit altered trafficking or retention within the cytoplasm, potentially influencing their stemness-related functions." (PMID 41176605, 2025). "The present study summarizes for the first time the evidence available in the literature on the expression of stem cell gene markers in odontogenic tumors and cysts, and further highlights the usefulness of SOX2 in the differential diagnosis of odontogenic lesions with divergent biological behavior." (PMID 37761874, 2023). "Additionally, functional assays such as SOX2 knockdown/overexpression in odontogenic tumor cell lines, coupled with pathway analysis, could validate SOX2 role in recurrence and invasiveness." (PMID 41176605, 2025). "Immunohistochemical staining for SOX-2, NANOG and OCT4 was mainly located in the cords and islands of the odontogenic tumour epithelium." (PMID 36655039, 2023). "The weak or absent expression of SOX2 in AB specimens found in the present study could imply that this particular odontogenic tumor presents another molecular pathway responsible for conserving its neoplastic behavior." (PMID 31967981, 2020).
oral epithelial dysplasia (5 papers, 2014 to 2025). "Nuclear SOX2 expression was detected in four (7%) cases of oral epithelial dysplasia, using a cut-off of 10% stained nuclei, and in 16 (29%) cases when any positive nuclei was evaluated." (PMID 31640140, 2019). "SOX2 expression was evaluated by immunohistochemistry in 55 patients with oral epithelial dysplasia, and in 125 patients with OSCC, and correlated with clinicopathological data and outcomes." (PMID 31640140, 2019). "Comparison of ALDH1, SOX2, CD44, and OCT4 Values between p16-positive and p16-negative Oral Epithelial Dysplasia." (PMID 34709167, 2021). "Following analysis, we observed that the mean expression scores of SOX2 were 117.6 ± 2.8 (n = 43), 205.9 ± 10.7, and 40.2 ± 5.9 in OSCC, oral epithelial dysplasia, and normal mucosa, respectively." (PMID 24883329, 2014). "In addition, a significant difference in SOX2 staining was demonstrated between OSCC, oral epithelial dysplasia, and normal oral mucosa (P < 0.05)." (PMID 24883329, 2014).
rhabdomyosarcoma (5 papers, 2015 to 2023). A rare aggressive malignant mesenchymal neoplasm arising from skeletal muscle. "The lncRNA named rhabdomyosarcoma associated transcript (RMST) mediates the binding of the SRY-Box Transcription Factor 2 (SOX2) transcription factor to its binding sites and play a role in neuronal differentiation." (PMID 35359941, 2022). "One of the articles reported no results using the cellular line of rhabdomyosarcoma, and the other found overexpression of ALDHA3, ALDHB1, ALDHL2, SOX2, ABCG2, ABCB1, and ABCA2 markers." (PMID 37173919, 2023).
Septo-optic dysplasia (5 papers, 2014 to 2025). Septooptic dysplasia (SOD) is a clinically heterogeneous disorder characterized by the classical triad of optic nerve hypoplasia, pituitary hormone abnormalities and midline brain defects. "Besides, mice with mutations in Sox2 or Sox3, used as animal models of septo-optic dysplasia, display downregulation of Shh expression." (PMID 33324176, 2020). "In septo-optic dysplasia there are few family cases, the majority of cases being sporadic; thus, less than 1% of septo-optic dysplasia patients have mutations in the genes Hesx1, Sox2, Sox3, or Otx2." (PMID 33324176, 2020). "Indeed, mutations in signaling molecules (e.g., SHH and FGFs) and transcription factors (e.g., SIX3, SOX2, and SOX3) have been implicated in midline forebrain defects such as septo-optic dysplasia and holoprosencephaly." (PMID 33324176, 2020).
type 1 diabetes (5 papers, 2010 to 2024). "In type 1 diabetic mice and high glucose-cultured HK-2 cells, it was demonstrated that circ_ASAP2 binding to miR-770-5p reduced inflammation and ferroptosis by regulating the SRY-box transcription factor 2 (SOX2)/SLC7A11 pathway." (PMID 37324941, 2023). "In human type 1 diabetes (T1D) pancreatic islets, fasting conditions reduce PKA and mTOR activity and induce Sox2 and Ngn3 expression and insulin production." (PMID 34067055, 2021).
acute myeloid leukemia (4 papers, 2020 to 2026). Acute myeloid leukemia (AML) is a group of neoplasms arising from precursor cells committed to the myeloid cell-line differentiation. "Besides, overexpression of FTO in acute myeloid leukemia cells could decrease m6A modification of NANOG and SOX2 and increase their mRNA levels, which was consistent with our studies in HCC cells." (PMID 33783988, 2021).
adenoid cystic carcinoma (4 papers, 2014 to 2024). A malignant tumor arising from the epithelial cells. "The present study aimed to investigate the clinicopathological and prognostic significance of SOX2 in adenoid cystic carcinoma (ACC) of salivary gland." (PMID 24828201, 2014). "Also of note, silencing of SOX2 by brachyury knockdown inhibited epithelial-mesenchymal transition (EMT) in adenoid cystic carcinoma." (PMID 24828201, 2014). "Among the tumors that originate in the sinonasal cavities, the amplification and/or overexpression of Sox2 was demonstrated in squamous sinonasal carcinoma (SNSCC), SNUC, adenoid cystic carcinomas (ACCs), and ITAC." (PMID 37888115, 2023). "However, the role of SOX2 in salivary gland malignancies like the adenoid cystic carcinoma (ACC) has not been sufficiently elucidated." (PMID 29596469, 2018).
ameloblastic carcinoma (4 papers, 2020 to 2023). A rare, cytologically malignant ameloblastoma that may metastasize. "In addition, SOX2 was shown to be overexpressed in ameloblastic carcinomas and the strong nuclear immunohistochemical staining of SOX2 was associated with the high-grade transformation of AMs." (PMID 34261507, 2021).
anaplastic large cell lymphoma (4 papers, 2016 to 2019). Anaplastic large cell lymphoma (ALCL) is a rare and aggressive peripheral T-cell non-Hodgkin lymphoma, belonging to the group of CD30-positive lymphoproliferative disorders, which affects lymph nodes and extranodal sites. "MYC increases SOX2 transcriptional activity, forming a positive-feedback loop involving the Wnt/β-catenin/MYC/SOX2 axis, which defines a highly tumorigenic cell subpopulation in ALK-positive anaplastic large cell lymphomas." (PMID 30688660, 2019).
Anxiety (4 papers, 2013 to 2023). Intense feelings of nervousness, tension, or panic often arise in response to interpersonal stresses. "However, Cckbr-/- mice also have blunted stress responses associated with anxiety-like behavior and increased Npy expression, which resembles the phenotype of Sox2-Cre:Errβlox/lox mice." (PMID 24053666, 2013). "Sox2 cKO mice displayed heightened anxiety in the elevated plus maze, reduced depressive-like behavior in the forced swim and tail suspension tests, and decreased sucrose preference." (PMID 34842772, 2021). "Here, we demonstrate that selective ablation of Sox2 in the SCN alters anxiety- and depressive-like behaviors in mice." (PMID 34842772, 2021). "Using the EPM as a test of anxiety, we find that Sox2 cKO mice were much less inclined to explore the maze, as indicated by the reduced frequency of entry into any arm, and they almost never entered the open arms." (PMID 34842772, 2021). "Based on Anyan and Amir’s reinterpretation of the FST, we propose that reduced immobility in the FST and TST is the consequence of a heightened state of anxiety in Sox2 cKO mice, consistent with their behavior in the EPM." (PMID 34842772, 2021). "Results from our Sox2 cKO mice are in line with studies that positively correlate circadian disturbances with an increase in anxiety-like behaviors." (PMID 34842772, 2021). "Here, we show that Sox2 ablation in the SCN perturbs anxiety- and depressive-like behaviors in mice." (PMID 34842772, 2021). "To determine whether ablation of Sox2 in the SCN impacts anxiety- and depressive-like behaviors, we subjected Sox2 cKO mice and Sox2fl/fl controls to four behavioral paradigms established to assess a rodent’s affective state." (PMID 34842772, 2021). "The present study established that PH aggravated anxiety-like depressive behaviors in MSG-treated rats, concordant with damaged Nissl bodies (and neurites), decreased IBA-1 and Sox-2 expression in OFC and neurotransmitter disorder." (PMID 31798487, 2019).
breast adenocarcinoma (4 papers, 2016 to 2023). "Using human tissue microarrays of breast adenocarcinoma, SOX2 expression was determined to be higher in tumor tissues than in adjacent nontumor tissues, and the expression level of TRIB3 correlated with the expression level of SOX2 in tumor tissues." (PMID 31844113, 2019).
cervical (4 papers, 2014 to 2025). "Further studies with larger numbers of patients and molecular insights should focus on the diagnostic and prognostic significance of NANOG and SOX2 in the entire process of cervical carcinogenesis." (PMID 40272007, 2025). "The array data analysis performed with GEO2R showed that the expression of CBP/β-catenin and its target genes of KLF4, MYC, and SOX2 were upregulated, generally synchronicity with the progression of cervical lesion grade." (PMID 34257574, 2021). "Our results show that Oct4, as well as other stemness markers such as Sox2 and Klf4, are indeed enriched in the cervical tumorspheres compared to the cancer cell monolayers and this was true in all conditions tested." (PMID 32298395, 2020).
chronic myeloid leukemia (4 papers, 2016 to 2025). "Hypoxia can increase the expression of the stem cell markers c‐MYC, NANOG, SOX2 and OCT4 in chronic myeloid leukaemia (CML) tumour cells." (PMID 32588948, 2020).
cognitive decline (4 papers, 2014 to 2024). "Resveratrol, an activator of SIRT1, can activate SIRT1 in aged POCD mice, reverse the decrease of sex-determining region Y-box-2 (Sox2) induced by anesthesia/surgery and alleviating cognitive decline in aged POCD mice." (PMID 38783169, 2024). "Consistent the results of previous studies, our findings confirmed that the cognitive decline in mice after surgery is related to the decrease in SOX2 expression." (PMID 37098623, 2023).
cutaneous squamous cell carcinoma (4 papers, 2020 to 2026). "In cutaneous squamous cell carcinomas, chromatin immunoprecipitation–sequencing experiments indicated that Sox-2 directly regulates gene networks promoting cancer stemness, proliferation, and cell survival." (PMID 34546978, 2021).
diffuse large B-cell lymphoma (4 papers, 2020 to 2025). "Recently, it was demonstrated that the PI3K/AKT/SOX2 axis has a significant role in the development of R-CHOP resistance in the proportion of cancer stem-like cells (CSCs) in diffuse large B cell lymphoma." (PMID 35309116, 2022).
ischemia (4 papers, 2016 to 2025). A hypoperfusion of the BLOOD through an organ or tissue caused by a PATHOLOGIC CONSTRICTION or obstruction of its BLOOD VESSELS, or an absence of BLOOD CIRCULATION. "It was reported that Shh is a direct target gene of Sox2 and is up-regulated after ischemia, as it can modulate adult hippocampal neurogenesis." (PMID 28066182, 2016). "These ischemia/injury-induced multipotent stem cells (iSCs) expressed not only pericytic markers (e.g., PDGFRβ, neural/glial antigen 2 (NG2), and alpha-smooth muscle actin (αSMA)), but also various stem cell markers (e.g., nestin, c-myc, Klf4, and Sox2)." (PMID 32887241, 2020).
leiomyoma (4 papers, 2017 to 2023). A well-circumscribed benign smooth muscle neoplasm characterized by the presence of spindle cells with cigar-shaped nuclei, interlacing fascicles, and a whorled pattern. "The involvement of many proteins such as FN1, COL1A1, BMP7, CCND1, EZH2, HMGA2, AhR, and E2F1 shown in the protein–protein interaction networks are well known in leiomyoma pathogenesis; others, such as SOX2, REN, PPARG, ABCB1, and NR3C1 are novel and require further investigation." (PMID 36835153, 2023). "Both cell types expressed NANGO, OCT4, SOX2, and KLF4, tested by RT-PCR and cytofluorometry, with a higher expression in leiomyoma cells." (PMID 29861738, 2018).
malignant mesothelioma (4 papers, 2020 to 2024). A malignant neoplasm of the pleura or peritoneum, arising from mesothelial cells. "CSCs in malignant mesothelioma represent cell subpopulations that can be identified by the expression of specific markers such as Oct4 and SOX2." (PMID 35883451, 2022). "CSC subpopulations in malignant mesothelioma were identified by the expression of the transcription factors Sox2 and Oct4, working together to regulate genes required for the self-renewal and pluripotency of embryonic stem cells (ESCs)." (PMID 35883451, 2022). "For the first time, we showed that genes and proteins of pluripotency factors NANOG and SOX2 are expressed in normal mesothelium and malignant mesothelioma." (PMID 32664372, 2020).